HOTAIR (HOX transcript antisense RNA)
Diseases named in the same sentence as HOTAIR in open-access papers (continued):
Sharing a sentence is not in itself a finding about the gene and the disease.
ovarian carcinoma (continued). "Moreover, it has been reported that exogenous HOTAIR overexpression in ovarian cancer cells significantly promoted cisplatin resistance by regulating the Wnt/β-catenin signaling pathway as well as the NF-κB-HOTAIR axis, indicating that HOTAIR may act as a regulator of cisplatin resistance." (PMID 34512721, 2021). "It was suggested that the regulation of some long non-coding RNAs, such as HOTAIR, UCA1, HOXA11AS, etc., through RNAi techniques or CRISPR/Cas-9 was thought to be a promising therapy for ovarian cancer." (PMID 34765618, 2021). "The expression of both HOTAIR and PIK3R3 was downregulated when ovarian cancer cells were transfected with miR-214 or miR-217 mimics." (PMID 34204094, 2021). "Interestingly, our data showed that downregulation of miR-138-5p only partially reversed the HOTAIR silencing-mediated pro-apoptosis activity, suggesting that other miRNAs or molecules may also contribute to the action of HOTAIR on chemosensitivity of ovarian cancer cells to DDP." (PMID 32349783, 2020). "In this study, we detected the expression of HOTAIR and miR-138-5p in DDP-resistant cells and investigated correlation effects of HOTAIR and miR-138-5p in DDP resistant ovarian cancer cells." (PMID 32349783, 2020). "A qualitative evaluation of ovarian cancer revealed the top 20 predictions by LION contained all four experimentally validated lncRNAs: MALAT1, H19, HOTAIR, and PVT1." (PMID 31379598, 2019). "The 5-prime region of HOXA includes three lncRNAs, HOTTIP, HOXA11-AS, and HOXA10-AS and studies found that HOTAIR and HOXA11-AS were dysregulated in ovarian cancer." (PMID 29921308, 2018). "Other lncRNAs have also been shown to be associated with ovarian cancer development and metastasis, including HOTAIR, H19, GAS5, and UCA1; however, to date, little was known about linc-ROR in ovarian cancer." (PMID 29050257, 2017). "Many lncRNAs, such as HOTAIR, H19, MEG3, and UCA1, have been recognized as key regulators of the occurrence and development of ovarian cancer." (PMID 29050257, 2017). "HOTAIR regulates CCND1 and CCND2 expression by sponging miR-206 in ovarian cancer." (PMID 32349783, 2020). "In another study, HOTAIR was demonstrated to enhance the expression of CCND1 and CCD2 by negatively modulating the expression of miR-206 and stimulating the proliferation, cell cycle progression, migration, and invasion of ovarian cancer cells." (PMID 32785167, 2020). "An approximate 1600-fold increase in ALDH1A1 expression was detected as well as a 3-fold increase in HOTAIR expression in ALDH1A1 positive ovarian cancer cells relative to negative cells." (PMID 28420874, 2017). "Considering the data from ectopic overexpression and the report of a lack of HOXD10 induction after HOTAIR knockdown in ovarian cancer cells, our finding strongly argues that HOTAIR target genes are tissue-specific." (PMID 25994132, 2015). "As HOTAIR is known to modulate chromatin, in particular at PCGTs, we asked if DNAme differed between HOTAIR-expressing and non-expressing ovarian cancer samples." (PMID 26497652, 2015). "The following researches confirmed that HOTAIR negatively regulated miR-206 to activate STS2 33 to promote cancer invasion of head and neck squamous cell carcinoma as well as to activate CCND1 and CCND2 34 to stimulate the proliferation, and invasion of ovarian cancer cells." (PMID 32489462, 2020). "However, HOTAIR expression in ovarian cancer tissues was not reported in this first study." (PMID 34204094, 2021). "Moreover, there is no report about the correlation between HOTAIR and miR-138-5p on regulating DDP resistance in ovarian cancer cells." (PMID 32349783, 2020).
pancreatic cancer (74 papers, 2013 to 2025). "The rs200349340 and rs4759314 polymorphisms of the HOTAIR gene are associated with pancreatic cancer." (PMID 38559560, 2024). "A high expression of HOTAIR was also associated with proliferation and the metastasis of pancreatic cancers." (PMID 34439315, 2021). "It was found that a higher level of HOTAIR had strong associations with susceptibility of pancreatic cancer." (PMID 34439315, 2021). "The minor alleles of HOTAIR rs4759314 and rs200349340 were significantly associated with pancreatic cancer susceptibility." (PMID 32394637, 2020). "Gene set enrichment analysis suggests that HOTAIR regulates genes sets mainly associated with cell cycle progression and cell proliferation, and down-regulation of HOTAIR results in a decrease in pancreatic cancer cell proliferation." (PMID 27895308, 2016). "The analysis of the predictions obtained by our algorithm has provided the association with lncRNA HOTAIR, whose overexpression has been associated with a poor prognosis in pancreatic cancer, as well as show a pro-oncogenic activity." (PMID 25566534, 2014). "HOTAIR is also important as a diagnostic biomarker in pancreatic cancer patients." (PMID 38559560, 2024). "Moreover, polymorphisms such as rs4759314 and rs200349340 increase HOTAIR expression and promote pancreatic cancer susceptibility." (PMID 34178644, 2021). "Furthermore, HOTAIR expression was associated with more aggressive pancreatic cancer, suggesting its prognostic role in pancreatic cancer." (PMID 34439315, 2021). "Based on previous studies in pancreatic cancer, several lncRNAs including plasmacytoma variant translocation 1, metastasis-associated lung adenocarcinoma transcript 1, H19, HOTAIR, and HOTTIP exhibit pro-oncogenic activities and correlate with unfavorable outcomes." (PMID 27895308, 2016). "MiR-34a is another direct target of HOTAIR that is downregulated through enhancer of zeste 2 polycomb repressive complex 2 subunit (EKH2) mechanisms during pancreatic cancer." (PMID 38559560, 2024). "HOTAIR also regulates the expression of miRNAs and modulates key signaling pathways involved in pancreatic cancer progression." (PMID 38559560, 2024). "As a result, HOTAIR is involved in increasing cellular energy levels and growth induction in pancreatic cancer cells." (PMID 38559560, 2024). "By contrast, the HOTAIR downregulation was shown to enhance radiosensitivity in pancreatic cancer and CRC." (PMID 39055884, 2024). "As a prognostic biomarker, HOTAIR expression in the late stages of pancreatic cancer indicates poor patient survival and cancer progression." (PMID 38559560, 2024). "HOTAIR is expressed in high levels in pancreatic cancer tissues compared to adjacent normal cells and significantly increases the cell’s ability for proliferation, invasion, and metastasis." (PMID 38559560, 2024). "HOTAIR is one of the most important lncRNAs in pancreatic cancer, which is involved in regulating neighboring homeobox (HOX) genes." (PMID 38559560, 2024). "By contrast, the inhibition of HOTAIR enhances radiosensitivity in pancreatic cancer cells by regulating autophagy." (PMID 39055884, 2024). "Consistent with our results, HOTAIR silencing inhibited the canonical Wnt pathway in gastric and pancreatic cancer cells and in OA chondrocytes." (PMID 38071204, 2023). "In pancreatic cancer, high HOTAIR expression expedited cell resistance to TNF-related apoptosis-inducing ligand (TRAIL)-induced apoptosis through modulation of TRAIL receptor death receptor 5 expression." (PMID 36100611, 2022). "HOTAIR is highly expressed in liver, lung, and pancreatic cancers and can significantly promote the metastasis of these tumors." (PMID 34362879, 2021). "In pancreatic cancer, HOTAIR acts as a miRNA sponge for other miRNAs to modulate different crucial pathways involved in tumor progression." (PMID 33540611, 2021).
pancreatic cancer (continued). "Cancer studies have indicated that HOTAIR, as one of the best known lncRNAs, is overexpressed in numerous malignancies, including breast, colorectal, renal, and pancreatic cancers." (PMID 31208095, 2019). "For example, HOTAIR can promote pancreatic cancer cell proliferation by suppressing the expression of miR-663b via remodeling the chromatin structure within the miR-663b promoter." (PMID 31195674, 2019). "Knockdown of HOTAIR (siHOTAIR) by RNA interference shows that HOTAIR plays an important role in pancreatic cancer cell invasion." (PMID 30309340, 2018). "We have previously reported that the lncRNAs HOTAIR and HOTTIP regulate expression of genes associated with pancreatic cancer cell proliferation, survival and migration." (PMID 29389953, 2018). "The expression level of HOTAIR was further confirmed to be up-regulated in the pancreatic cancer tissues when compared to that in adjacent normal pancreatic tissues." (PMID 28415631, 2017). "Transfection with HOTAIR siRNA markedly suppressed the expression level of HOTAIR, and also increased the expression level of miR-613 in pancreatic cancer cells when compared to cells transfected with scrambled miRNA." (PMID 28415631, 2017). "More importantly, the expression level of miR-613 was inversely correlated with the expression level of HOTAIR in the pancreatic cancer tissues." (PMID 28415631, 2017). "In agreement with previous study, HOTAIR was up-regulated in pancreatic cancer cells when compared to that in adjacent normal pancreatic tissues." (PMID 28415631, 2017). "Consistently, our data showed that HOTAIR was found to be up-regulated in both pancreatic cancer tissues and cell lines, and HOTAIR was inversely correlated with miR-613 level in pancreatic cancer tissues." (PMID 28415631, 2017). "In pancreatic cancer cells, HOTAIR plays the role of ceRNA, combines with miR-613, increased the expression of Notch3, and promoted pancreatic cancer cell proliferation, migration and invasion." (PMID 29132362, 2017). "A few lncRNAs (HOTAIR, HULC, MALAT1, HOTTIP) have been found to be associated with pancreatic cancer." (PMID 28294968, 2017). "HOTTIP was observed to have pro-oncogenic functions in pancreatic cancer, similar to that of HOTAIR, although they elicit their effects through different pathways, leading to the expression of different sets of genes." (PMID 28294968, 2017). "Bioinformatics analysis and luciferase reporter assay showed that HOTAIR suppressed the expression miR-613 via sponging miR-613 in the pancreatic cancer cells." (PMID 28415631, 2017). "Our previous study showed that HOTAIR regulated the expression of miR-663b via histone modification in pancreatic cancer." (PMID 28415631, 2017). "The long non-coding RNA, HOX transcript antisense RNA (HOTAIR) was up-regulated in both pancreatic cancer tissues and cancer cell lines, and HOTAIR suppressed the expression of miR-613 via functioning as a competing endogenous RNA." (PMID 28415631, 2017). "In conclusion, the present study identified the interaction between HOTAIR and miR613 in pancreatic cancer." (PMID 28415631, 2017). "Collectively, these results suggest that the interaction between miR-663b and HOTAIR is key for the pancreatic cancer development." (PMID 27895308, 2016). "Five well-documented lncRNAs: H19, HOTAIR, HOTTIP, MALAT1, PVT1, which are most closely associated with pancreatic cancer from previous studies were selected as putative lncRNA biomarkers." (PMID 27028998, 2016). "In this study, HOTAIR was found to be up-regulated in both pancreatic cancer cell lines and pancreatic cancer tissues, and HOTAIR level was inversely correlated with miR-663b level in pancreatic cancer tissues." (PMID 27895308, 2016). "HOTAIR has been found to regulate miRNA levels in different types of cancers, and in the present study, the effect of HOTAIR on the miR-663b level was further explored in pancreatic cancer cells." (PMID 27895308, 2016).
pancreatic cancer (continued). "In summary, these results suggest that HOTAIR down-regulated miR-663b via histone modification in pancreatic cancer." (PMID 27895308, 2016). "In vitro mechanistic studies revealed the tumor suppressive role of miR-663b via targeting IGF2 in pancreatic cancer, and further study showed that HOTAIR-mediated down-regulation of miR-663b was via regulating histone modification." (PMID 27895308, 2016). "In the present study, we investigated the expression and function of HOTTIP in pancreatic cancer cells and compared the results to that observed in previous studies on HOTAIR in pancreatic cancer cells." (PMID 25912306, 2015). "Another microarray study of pancreatic cancer showed that GDF15 was regulated by both HOTAIR and PRC2." (PMID 25428914, 2015). "Results of knockdown and overexpression studies show that HOTTIP has functions comparable to that described for HOTAIR and plays a role in pancreatic cancer cell proliferation, survival and migration/invasion." (PMID 25912306, 2015). "Different studies revealed that increasing the expression of HOTAIR has several effects, such as increasing the proliferation and aggression of cancer cells in pancreatic cancer tissues." (PMID 25859406, 2015). "Previous studies in this laboratory showed that knockdown of HOTAIR in pancreatic cancer cells decreased proliferation, induced apoptosis, and inhibited invasion, and this was associated with changes in expression of genes associated with these pathways." (PMID 25912306, 2015). "In pancreatic cancer, HOTAIR levels were also increased in tumorigenic tissues compared to the non-tumorigenic tissues, and associated with a more aggressive phenotype." (PMID 24013378, 2013). "For example, elevation of HOTAIR promotes invasiveness and metastasis in the primary breast tumor; however, it decreases cell proliferation and induces apoptosis in the pancreatic cancer cells." (PMID 24223182, 2013). "Furthermore, HOTAIR detection in urine is associated with high-grade muscle-invasive disease in bladder cancer patients and salivary HOTAIR levels are significantly increased in pancreatic cancer patients compared with healthy controls." (PMID 38887279, 2024). "HOTAIR is also involved in the modulation of radioresistance in pancreatic cancer." (PMID 38887279, 2024). "Furthermore, upregulation of HOTAIR attenuated cell apoptosis induced by TNF-related apoptosis-inducing ligand (TRAIL) in pancreatic cancer." (PMID 35984196, 2022). "In addition, several ncRNAs such as AFAP1-AS1, UCA1, HOTAIR, PVT1, MALAT-1, circ-ADAM9, BC008363, circ-LDLRAD3, circ-IARS, circ-PDE8A, circ_0030235, and circ_0001649 have been associated with prognosis of pancreatic cancer." (PMID 34439315, 2021). "Knockdown of HOTAIR enhanced the radiosensitivity of pancreatic cancer." (PMID 34439315, 2021). "HOTAIR is another lncRNA which is highly expressed in pancreatic cancer." (PMID 34439315, 2021). "HOTAIR could also couple with EZH2 to silence tumor suppressor miR-34a in pancreatic cancer cells, thereby inducing cancer cell proliferation, suggesting the regulatory role of HOTAIR in EZH2/EMT pathway." (PMID 34439315, 2021). "It has been reported that HOTAIR could regulate the expression of Notch3 by acting as ceRNA to sponge miR-613 in the context of pancreatic cancer." (PMID 33461171, 2021). "Similarly, a recent study pointed out that HOTAIR knockdown enhanced radiosensitivity by inhibiting autophagy in pancreatic cancer cells." (PMID 32144238, 2020). "Furthermore, knockout of HOTAIR in the pancreatic cancer cell lines Panc-1 and L3.6Pl significantly decreases the progression of cells and interacts with the Polycomb Repressive Complex 2 (PRC2)." (PMID 32257946, 2020). "In pancreatic cancer, the expression of HOTAIR and PVT1 was upregulated." (PMID 31208095, 2019).
pancreatic cancer (continued). "Thus, results of this study confirm the pro-oncogenic activity of MALAT-1 in pancreatic cancer cells and demonstrate that this activity is distinct from that previously observed for HOTAIR and HOTTIP in Panc1 cells." (PMID 29389953, 2018). "Thus, although SNHG15 and HOTAIR have similar functions in pancreatic cancer, they differ in terms of target genes and their mechanisms of action." (PMID 29137412, 2017). "In summary, our results suggest the interaction between HOTAIR and miR-613 via “competing endogenous RNA” mechanism may be important for the pancreatic cancer progression." (PMID 28415631, 2017). "HOTAIR was found to play an important role in pancreatic cancer progression, which has been shown in our previous study, and we further examined whether miR-613 had an interaction with HOTAIR." (PMID 28415631, 2017). "Whether HOTAIR also functions as a competing endogenous RNA to regulate pancreatic cancer progression is largely unknown." (PMID 28415631, 2017). "Furthermore, HOTAIR was found to suppress the expression level of miR-663b in pancreatic cancer cells by modifying histone methylation on miR-663b promoter." (PMID 27895308, 2016). "Moreover, HOTAIR disrupted the balance between H3K4me3 and H3K27me3 on the miR-663b promoter region, which may be associated with the hypermethylation status of miR-663b in the pancreatic cancer cells; thus HOTAIR suppressed the expression of miR-663b in pancreatic cancer cells." (PMID 27895308, 2016). "HOTAIR expression levels correlate with enhanced tumor metastasis and can serve as a negative prognostic marker for breast, colon, liver, esophageal squamous cell and pancreatic cancer patients." (PMID 26578588, 2016). "We have now investigated the role of HOTTIP in pancreatic cancer cells and have observed pro-oncogenic functions similar to that reported for HOTAIR, even though both lncRNAs elicit their effects by regulating expression of different sets of genes by different pathways." (PMID 25912306, 2015). "However, the most striking observation was the minimal overlap between the genes regulated by HOTTIP vs. HOTAIR, further confirming the independent pro-oncogenic functions and gene regulation by these two lncRNAs in pancreatic cancer." (PMID 25912306, 2015). "HOTAIR could be another prognostic markers for pancreatic cancer." (PMID 34439315, 2021). "HOTAIR has been shown to function as an oncogene since its expression is dysregulated in multiple types of cancers, including breast, lung, liver, renal, hepatocellular, gastric, nasopharyngeal, cervical, colorectal, bladder, pancreatic cancer, as well as melanoma, leukemia, etc.." (PMID 31195674, 2019). "However, the functional role of HOTAIR is largely still unclear in pancreatic cancer." (PMID 27895308, 2016). "HOTAIR has been found to be overexpressed in a variety of human cancers and determined to be a negative prognostic indicator in breast, colon, liver, and pancreatic cancer patient survival, evidencing a close association with increase in cancer cell metastasis." (PMID 24155936, 2013). "HOTAIR directly regulates miR-34a expression, binding to its promoter, and it is able to repress miR-34a expression through EZH2 mechanisms in pancreatic cancer cells." (PMID 33540611, 2021). "A recent study showed that HOTAIR serves as up-stream regulator of HK2, an enzyme that catalyzes the first step of glycolysis and thus boosting cancer cell proliferation in pancreatic cancer cells." (PMID 34178644, 2021). "In a similar fashion, HOTAIR epigenetically silences miR-663b to upregulate its target IGF2 (insulin like growth factor 2) and promote pancreatic cancer growth." (PMID 29702599, 2018). "In previous studies, HOTAIR and PVT1 were demonstrated to be novel biomarkers for the early diagnosis of pancreatic cancer." (PMID 29207609, 2017).